CD4 (CD4 molecule)
Diseases named in the same sentence as CD4 in open-access papers (continued):
Sharing a sentence is not in itself a finding about the gene and the disease.
infection (continued). "We hypothesise that repeated episodes of sub-clinical CMV replication in AAV patients drive the expansion and possible functional impairment of CD4 + CD28null CMV-specific cells with a resultant increased susceptibility to infection." (PMID 27450392, 2016). "Thus, the impact of the protective and disease-susceptible HLA alleles on CD4 count is marked in adult infection, but is barely discernible in pediatric infection." (PMID 26076345, 2015). "Moreover, the number of IL-5- and IL-13-producing CD4 T cells was significantly (p<0.01) reduced in FI-RSV-immunized STAT6-deficient mice at day 7 post-infection." (PMID 25769044, 2015). "Moreover, despite their similar HLA class I alleles, R880F and R463F exhibited very different VL and CD4 count trajectories during the first year of infection." (PMID 25569444, 2015). "Rectal transmission is considered to be the easiest mucosal route for viral acquisition, where HIV-1 and HIV-infected cells transgress the epithelial layer via small breaks to cause systemic diffusion of the virus following the infection of numerous target CD4+/CCR5+ T lymphocytes." (PMID 29061947, 2015). "Together, the direction and magnitude of our point estimates suggest that we may have lacked the power to detect a positive association between HIV and HPV16/18 infections as well as higher risk for men with lower CD4+ cell counts over men with higher values." (PMID 25794147, 2015). "In this paper, we have used mouse models of erythrocytic P. chabaudi and P. yoelii 17X(NL) infections in combination with IL-21/IL-21R deficiency to show that IL-21 from CD4+ T cells is required to eliminate Plasmodium infection by activating protective, long-lasting B-cell responses." (PMID 25763578, 2015). "SIV infection was accompanied by a near total loss of CD4+ T cells in the oral mucosa that mirrored their loss in the rectal mucosa suggesting that oral mucosal immunity is significantly compromised as in the GIT during chronic stages of infection." (PMID 26065003, 2015). "The accumulation of activated memory CD4 cells could reflect homeostatic proliferation, an attempt to control underlying infection or secondary effects of transient high level Itpkb expression in the thymus." (PMID 26121493, 2015). "We hypothesized that immune activation from this gastrointestinal mucosa infection would increase highly HIV-susceptible CD4 T cell subsets in the blood and the foreskin through common mucosal homing." (PMID 26335139, 2015). "Furthermore, the lungs of wild-type mice revealed significantly increased total counts of CD4+ expressing IFN-γ during the whole infection period in comparison to Fas- and FasL-deficient mice (P ≤ 0.05)." (PMID 25873756, 2015). "We found that CD4-Cre; Ezh2fl/fl mice exhibited a significantly increased mortality rate compared with control animals, with the majority of the Ezh2-deficient animals dying in the second and third weeks post infection." (PMID 26090605, 2015). "Indeed, in our assay, unstimulated cells infected with a virus encoding nef have undetectable levels of CD4 by 3 days after infection and become resistant to infection with a second virus." (PMID 26559763, 2015). "Loss of CD4+ T cell help during the acute phase of infection might facilitate the initial emergence of escape variants." (PMID 25537849, 2015). "In conclusion, we provide evidence for the induction of IL-10-associated apoptosis of CD4+ cells, which leads to the development of hyporesponsiveness in the lymph nodes draining the site of infection shortly after exposure to repeated doses of infective schistosome parasites." (PMID 25624353, 2015). "Recently, studies showed that the impairment of this Th1 response may be implicated in maintaining the infection, along with the emerging role of other T CD4+ cell subsets, including Treg and Th17 cells." (PMID 26525279, 2015). "The mucosal availability of these highly susceptible CD4 T cells may determine whether exposure to HIV results in infection." (PMID 26335139, 2015).
infection (continued). "Indeed, for this not to hold it must be the case that individuals with low SPVL continue to survive with low CD4 count for a disproportionately long time (compared to individuals with low CD4 counts caused by high SPVL infections)." (PMID 26609066, 2015). "The administration of LPS into peripheral blood causes T cell activation, activated CD4+ T cells are highly susceptible to infection by HIV-1, and the increased viral replication may further exacerbate the immune activation." (PMID 26713320, 2015). "In the presence of infection or under inflammatory conditions, DCs employ macropinocytosis to internalize the soluble pathogenic antigens, degrade them into antigenic peptides, and present these antigenic pMHC-II complexes to CD4+ T cells." (PMID 25688210, 2015). "HIV-mediated cell death can contribute to the loss of CD4+ T cells, but quantitative image analysis suggested that infection-induced cell death could be compensated by upregulated T cell division." (PMID 26709961, 2015). "The control CD98hc+/+-CD4 mice could readily control Leishmania major infection, while CD98hcf/f-CD4 mice were relatively susceptible to this infection because their foot pad swelling increased compared with CD98+/+-CD4 mice." (PMID 26444422, 2015). "Thus, our results show a peak in viral replication shortly after infection that 'spontaneously' resolved thereafter, accompanied by a loss in CD4+ T cells in the blood of infected animals." (PMID 26407077, 2015). "While a formal correlates of risk study identified two antibody-dependent correlates, there was a suggestion that CD4 responses might (albeit weakly) be associated inversely with the risk of infection." (PMID 25665096, 2015). "This same mechanism, possibly through CD4+ T cells, may have led to an increased risk of infection among the Ad5 seropositive and uncircumcised subgroups of male vaccine recipients." (PMID 25369172, 2014). "We also show that these Th2 subpopulations appear to have differing programs of regulation by both IL-10 and TGFβ in filarial-infected individuals and that definitive treatment (and subsequent cure) of this infection causes reversion of the CD4+ Th2 subpopulation expansion to normal levels." (PMID 24498448, 2014). "A better understanding of the differentiation process and the developmental relationship between pTFH subsets and lymph node TFH cells is critical for the establishment of reliable peripheral blood CD4 T cell correlates for monitoring infection- or vaccine-associated B cell responses." (PMID 24497824, 2014). "This suggests that an increased and/or more efficient proliferation of CD4+ TCM may be a mechanism underlying preserved CD4+ T cells after several years of infection, despite active virus replication." (PMID 25167059, 2014). "Alternatively, infection of CD14+ DCs could affect their capacity to induce regulatory CD4 T cells in the skin, a function that has been associated with CD14+ DCs and not with CD1c+ DCs." (PMID 25474532, 2014). "In addition, in primary infections of KTR, it was shown that asymptomatic infections were associated with appearance of IFN-γ-producing CD4+ T-cells, prior to the emergence of CD8+ T-cells." (PMID 25166270, 2014). "Interestingly, the V1/V2 glycan-specific antibodies PG9 and PG16 showed increased activity against the primary CD4+ T cell associated virus during cell-cell infection (IC50 = 0.60 μg/ml and 0.26 μg/ml)." (PMID 25700025, 2014). "In contrast, depletion of CD4+ T cells led to complete loss of infection-induced immunity." (PMID 25412267, 2014). "However, in a later study investigating T cell immunity in H1N1pdm virus-infected patients, CD4+ T cell responses were associated with more severe infection." (PMID 24971078, 2014). "Indeed, we observed that the acute phase of infection is characterized by expansion and differentiation of splenic CD4 T cells towards effector memory phenotypes associated with increased levels of Th1-related factors (IFN-γ and T-bet)." (PMID 24763747, 2014).
infection (continued). "It is difficult to speculate on the possible biological relationship between the CMV-reactive CD4+ T cells and susceptibility to infection." (PMID 25275464, 2014). "Also it is shown that HIV-1 should overcome the cortical actin barrier during early infection and predicts the different susceptibility of CD4+ T cells to be infected in terms of actin cytoskeleton dynamics driven by associated cellular factors." (PMID 25105875, 2014). "We refer to the idea that the PAMPs, associated with an infection, determine the Th1/Th2 phenotype of the effector CD4 T cells generated, as the PAMP hypothesis." (PMID 24684592, 2014). "This preliminary baseline survey may suggest that CRF01_AE infection was clearly related to a faster CD4+T cell loss, as compared to CRF07_BC infection." (PMID 24586795, 2014). "This inconsistency could be explained considering the plausible late stage of infection among our patients allowing the R5 viruses develop mutations that increase their cytophatic capacity on CD4 T cells." (PMID 25032817, 2014). "Therefore, the importance of CD28 costimulation in sustaining CD4+ T cells dependent memory antibody responses seems to be differentially affected by parasite causing the infection." (PMID 24516382, 2014). "Although HIV-1 subtype C strains (C-HIV) account for the majority of HIV-1 infections worldwide, the susceptibility of CD4+ memory T-cells to infection by CCR5- (R5) and CXCR4-using (X4) C-HIV is unknown." (PMID 25387392, 2014). "Of note, quiescent CD4 T-cells are particularly susceptible to death by caspase-1 mediated pyroptosis induced by accumulation of incomplete HIV reverse transcripts resulting from abortive infection." (PMID 25333710, 2014). "These cells harbor virus and propagate infection, resulting in CD4+ T cell loss within days." (PMID 25502752, 2014). "Infection of otherwise resistant C57Bl/6 mice with arginase-deficient (arg−/−) L. major causes chronic persistence of cutaneous lesions associated with exhaustion of specific CD4 T cells from the draining lymph nodes." (PMID 24551250, 2014). "While R5 strains are usually transmitted and predominate at early stages of infection, X4 variants are found in approximately 50% of subtype B infected patients in chronic stages of the disease and coincide with a rapid CD4 T-cell loss and an accelerated progression to AIDS (see reviews)." (PMID 24884925, 2014). "However, despite such discrepancies, these cells have been continuously implicated as carriers of infection to CD4+ T-cells, to local cells, and to associated lymphoid tissues." (PMID 25313360, 2014). "MDMs were cocultured directly, or across transwells, with CD4+ T cells infected independently with six different T/F viruses or two chronic M-tropic luciferase-encoding IMCs as before and assayed for infection." (PMID 25467409, 2014). "We focused here on a panel of SIV Envs derived from the plasma of rhesus macaques that had been experimentally depleted of CD4+ T cells prior to infection, in which CD4-independent virus variants arose in multiple animals in association with widespread macrophage infection." (PMID 24219995, 2013). "The high CD4 binding ability of the envelopes at this stage could be another compensatory mutation for more efficient infection in an environment with limited availability of CD4+ T cells." (PMID 23840566, 2013). "Importantly, the CD4+ effector-memory T cell (Tem) subset is most susceptible to trans infection by R5 HIV-1, which is related to expression of the CCR5 coreceptor." (PMID 24278768, 2013). "In a recent work, Yang and collaborators have reported that measuring early in infection the capacity of CD8+ T cell to suppress HIV may predict the rate of loss of CD4+ T cells." (PMID 23555774, 2013). "However, although X4-tropic viruses preferentially target Tregs, these cells are less susceptible to infection with R5-tropic HIV strains than conventional CD4+ T cells." (PMID 24257114, 2013).
infection (continued). "Males, younger people, people diagnosed in provinces Guangxi, Henan, Heilongjiang, Jiangxi, Shanghai and Yunnan, and persons who acquired the infection through unknown transmission route showed a higher risk of low CD4 count at HIV diagnosis." (PMID 24024658, 2013). "The degree of HIV sequence diversity has been associated with CD4 counts later in infection." (PMID 23331949, 2013). "However, other studies found that B-cell–deficient mice that also had their CD4+ cells depleted were completely unable to control secondary infection, whereas mice depleted of CD4+ cells alone only showed slight delay in clearing secondary infection." (PMID 23457650, 2013). "However, the total numbers of CD4+ T cells in Fas- and FasL- deficient mice at day 7 of infection were significantly lower (p≤0.01) in comparison to HSV-2 infected wild type strain at the same time point." (PMID 23922974, 2013). "It is possible that we may have underestimated the association of OIs with subsequent VL elevation and CD4+ T cell count decline because the study population were visited weekly at their home and most new infections were likely to be promptly treated." (PMID 23547778, 2013). "CD4+ lymphocytes increase during experimental infection of both susceptible and resistant sheep." (PMID 23509684, 2013). "There is also evidence that FIV can establish a latent infection in vivo following mucosal administration of low-dose cell-associated FIV-A, in peripheral blood CD4+ T-cells during chronic FIV-C infection, and in peripheral blood mononuclear cells (PBMC) during chronic FIV-B infection." (PMID 23829177, 2013). "However, upon treatment interruption, HIV-specific CD4+ T-cells are susceptible to infection, and hence, their critically important helper function is lost." (PMID 24287598, 2013). "In addition, transfer of monoclonal antibodies to Ct major outer membrane protein (MOMP) and LPS into B-cell–deficient, CD4+ T-cell–depleted mice restored the ability of these mice to control secondary infection." (PMID 23457650, 2013). "Second, broad HCV-specific CD4 T cell responses are induced early in most acutely infected individuals but they undergo progressive loss of IL-2 production and diminished proliferation as infections progress towards viral persistence." (PMID 23818845, 2013). "Evidence suggests that infectious virus particles sequestered within IC as well as virus produced by infected cells within GCs provide a source for new infections of activated CD4+ T lymphocytes and macrophages and facilitate ongoing CD4+ T cell loss, immune activation, and follicular dissolution." (PMID 23472105, 2013). "CD4+ T cells play a key role in immune control of Mtb infection, and multifunctional cytokine production of antigen-specific Th1 cells has been felt to be associated with control of infection." (PMID 23451159, 2013). "The decreased CD4 T cell response in OX40-deficient MCMV-infected animals is believed to be responsible for the observed slight decrease in the inflationary CD8 T cell response at later stages of infection." (PMID 23717308, 2013). "Activation of CD4+ T cells can result in a higher susceptibility for infection with HIV-1." (PMID 23724015, 2013). "We found that, whilst increasing in number, the IL-4gfp+CD4+ Th2 cells became conditioned towards a functionally hypo-responsive phenotype as infection progressed denoted by a progressive loss in their intrinsic ability to produce the cytokines IL-4, IL-5 and IL-2." (PMID 23516361, 2013). "Patients with advanced HIV-1 disease as measured by low CD4+ T cell blood count have the highest levels of T cell activation, concomitant with rapid proliferation and apoptosis, enhanced CD4+ T cell susceptibility to infection." (PMID 22879884, 2012). "Interestingly, normally resistant mice become more susceptible to infection with age due to a decreased ability of CD4+ T cells to respond to stimulation and to polarize into Th2 cells." (PMID 23053395, 2012).